CLCA1 (chloride channel accessory 1)
Diseases named in the same sentence as CLCA1 in open-access papers (continued):
Sharing a sentence is not in itself a finding about the gene and the disease.
infection (16 papers, 2009 to 2024). The state of being infected such as from the introduction of a foreign agent such as serum, vaccine, antigenic substance or organism. "The mucous cell-associated CLCA1 transcript was also one of the most up-regulated transcripts observed from immunized sheep in response to infection from ovine gastric nematode Teladorsagia circumcincta." (PMID 31871532, 2019). "Mice lacking MMP17 expressed high levels of goblet-cell associated genes and proteins, such as CLCA1 and RELM-β, which are normally associated with immune responses to infection." (PMID 37869014, 2023). "Retnlb, Clca1, and Ang4 can be classified as AMPs, which are typically upregulated in the intestine during infections." (PMID 37869014, 2023). "Mucus and goblet cell effector genes, such as Ang4, Clca1, and Retnlb are typically induced during infections by cytokines, especially IL-4, IL-13 and IL-22." (PMID 37869014, 2023). "Although Clca1 expression was higher, goblet cell-specific genes and Ctsz expression was lower in trained mice after infection." (PMID 37305694, 2023). "Clca1, Muc5ac, and Ccl11 were confirmed to be highly up-regulated during infection in WT mice but impaired in Il13−/− mice." (PMID 34127548, 2021). "A significantly higher percentage of BPIFA1-positive respiratory epithelial cells per 100 μm basement membrane was observed at 48 h after infection in Clca1−/− mice compared to WT mice in the distal trachea with 22.6 and 14.5% BPIFA1-expressing epithelial cells, respectively (p < 0.05)." (PMID 29610986, 2018). "Additionally, the intracellular infection also affects the electrolyte secretion by decreasing expression of the chloride channel gene (CLCA1)." (PMID 23800029, 2013). "Goblet cell effectors CLCA1, ANG4, and RELM-β are induced during infection with the helminth T. muris." (PMID 37869014, 2023). "Moreover, Clca1−/− mice infected with S. aureus had significantly higher numbers of BPIFA1-expressing respiratory epithelial cells 48 h after infection when compared to WT mice, arguing that modulation of BPIFA1 expression by respiratory epithelial cells may also be dependent on CLCA1." (PMID 29610986, 2018).
respiratory diseases (5 papers, 2014 to 2022). "CLCA1 is probably the best-studied member from the CLCA family prominently in human respiratory diseases." (PMID 31871532, 2019). "The top ten genes (Clca1, Chil4, Itln1, Tff1, Muc5ac, Clca3b, Chodl, Pla2g4c, Mmp10, and Stac2) with the highest fold change are involved in various inflammatory responses and respiratory diseases." (PMID 33066398, 2020). "Therefore, the role of CLCA1 in respiratory diseases might involve much more complicated downstream pathways, rather than just goblet cell mucus production and epithelial cell chloride ion secretion." (PMID 31871532, 2019). "CLCA1 is the most studied member of the CLCA family and mainly plays an important role in human respiratory diseases." (PMID 36313877, 2022).
gastrointestinal disease (2 papers, 2019 to 2022). A disease that occurs in the gastrointestinal system, excluding the hepatobiliary system. "Further understanding of CLCA1 function in mucus production helps probe the pathophysiology of gastrointestinal diseases and develop novel treatment for mucus production-associated complications by regulating CLCA1 expression." (PMID 31871532, 2019).
intestinal disease (2 papers, 2015). "A similar correlation has been found in humans where a certain allelic variant of CLCA1 is significantly overrepresented in CF patients with aggravated intestinal disease." (PMID 26162072, 2015).
CLCA1 also shares sentences with these, for which no sentence is quoted: chronic obstructive pulmonary disease (4 papers); rectal cancer (4); adenocarcinoma (2); eosinophilia (2); inflammation (2); Viral infection (2); AIDS (1); airway hyperresponsiveness (1); Airway obstruction (1); atopic asthma (1); bladder cancer (1); chronic lung disease (1); fibrosis (1); fungal infection (1); hepatocellular carcinoma (1); immune dysfunction (1); lung (1); Meconium ileus (1); Nephropathy (1); parasitic infections (1); pediatric asthma (1); spinal muscular atrophy (1).